PTPRC (protein tyrosine phosphatase receptor type C)
Diseases named in the same sentence as PTPRC in open-access papers (continued):
Sharing a sentence is not in itself a finding about the gene and the disease.
periodontitis (16 papers, 2019 to 2026). An acute or chronic inflammatory process that affects the tissues that surround and support the teeth. "The observed associations between PTPRC and disease progression in periodontitis and rheumatoid arthritis need further validation in experimental models, such as animal studies or clinical trials, to confirm causality." (PMID 39987090, 2025). "Collectively, PTPRC serves as a critical mediator within the inflammatory framework induced by PT, providing a molecular link between periodontitis and RA through its modulation of immune responses across multiple interconnected pathways." (PMID 39987090, 2025). "Western blot analysis demonstrated a significant increase in PTPRC expression in periodontal tissues from patients with periodontitis compared to controls." (PMID 39987090, 2025). "In conclusion, this study highlights the intricate molecular crosstalk between periodontitis and RA, identifying PTPRC as a potential key regulator in both diseases." (PMID 39987090, 2025). "The expression of KRT15, a basal epithelial marker, clearly delineated the boundary between the epithelium and the lamina propria, while PTPRC, a pan-immune marker, revealed the spatial infiltration of immune cells in periodontitis." (PMID 41358003, 2025). "To validate the role of PTPRC in periodontitis, we analyzed periodontal tissue samples from patients with periodontitis and healthy controls." (PMID 39987090, 2025). "RAC2 and PTPRC were significantly increased in the periodontitis (p<0.005) and periodontitis patients with T2DM group (p <0.005) compared with the healthy control group." (PMID 35145474, 2021). "Similarly, CD86, a critical co-stimulatory molecule involved in T-cell activation, and PTPRC (CD45), a regulator of immune cell signaling, underscore the immune involvement in periodontitis." (PMID 41140666, 2025). "Although this study observed significantly increased PTPRC expression in periodontitis tissues, it remains to be determined whether this overexpression directly influences RA onset or exacerbation." (PMID 39987090, 2025). "Given PTPRC's critical role in regulating immune cell activation and inflammation, targeting it could represent a promising therapeutic approach for diseases, such as rheumatoid arthritis (RA) and periodontitis." (PMID 39987090, 2025). "Furthermore, PTPRC may serve as a valuable biomarker for the early detection and monitoring of RA and periodontitis." (PMID 39987090, 2025). "PECAM-1 and PTPRC have not been reported in relation to periodontitis or peri-implantitis." (PMID 35581339, 2022).
cervical carcinoma (14 papers, 2008 to 2025). A carcinoma arising from either the exocervical squamous epithelium or the endocervical glandular epithelium. "PTPRC is used as a prognostic indicator of cervical cancer, but its specific role in SKCM is still unclear." (PMID 36032150, 2022). "Recently, it has been reported that overexpression of PTPRC is involved in cell adhesion, facilitating the tumour proliferation and lymph node metastasis in cervical cancer patients." (PMID 35286517, 2022). "However, only PTPRC showed overall survival in cervical cancer." (PMID 33946372, 2021). "Therefore, we speculate that PTPRC, which is enriched in an integral component of the plasma membrane, may be an important signal molecule in cervical cancer metastasis." (PMID 32457603, 2020). "The relative scores of total infiltrating lymphocytes (TILs) were calculated between the groups based on the expression of CD45 (PTPRC) and were found to be higher in all cervical cancer groups compared to HC." (PMID 35087740, 2021). "Among them, two miRNAs (miR-502 and miR-33b) and two key genes (PTPRC and CDH5) were first reported to be potential novel biomarkers for cervical cancer." (PMID 32457603, 2020). "We showed that four miRNAs (miR-502, miR-145, miR-142, and miR-33b) are independent and common prognostic biomarkers for patients with cervical cancer, and seven proteins (CXCL12, IGF1, PTPRC CDH5, RAD51B, REV3L, and WDHD1) are key genes significantly related to lymph node metastasis." (PMID 32457603, 2020). "Furthermore, based on the GSE168652 dataset of single‐cell RNA sequencing results of human cervical cancer tissues, we recognized six cancer cell subclusters, which were characterized by negative PTPRC (a marker of immune cells) and positive CDH1, CDKN2A, and EPCAM (markers of epithelial cells)." (PMID 36999964, 2023).
hepatocellular carcinoma (14 papers, 2013 to 2025). A malignant tumor that arises from hepatocytes. "Key markers, such as PTPRC, CD3E, CD4, CD79A, and CD3G in immune cells, EPCAM and KRT19 in epithelial cells, and MME and PECAM1 in stromal cells, were identified, providing crucial insights into hepatocellular carcinoma progression and immune response mechanisms." (PMID 39388011, 2024).
acute lymphoblastic leukemia (13 papers, 2006 to 2024). Leukemia with an acute onset, characterized by the presence of lymphoblasts in the bone marrow and the peripheral blood. "Furthermore, loss-of-function mutations in PTPRC, which encodes CD45, have been detected in acute lymphoblastic leukaemia, suggesting that CD45 may have tumour-suppressor activity." (PMID 38334623, 2024).
liver fibrosis (12 papers, 2016 to 2025). "In our study, PTPRC was up-regulated in kidney and liver fibrosis in CD with fibrosis and in CD without fibrosis; it was not significantly altered in UC." (PMID 35159124, 2022).
lung adenocarcinoma (12 papers, 2015 to 2025). A carcinoma that arises from the lung and is characterized by the presence of malignant glandular epithelial cells. "As lung adenocarcinomas are known to be highly infiltrated with immune cells, we looked for putative immune cell-derived lncRNAs that positively correlated with expression of PTPRC, encoding CD45 as a marker for leukocytes." (PMID 33037279, 2020).
type 1 diabetes (12 papers, 2017 to 2025). "Using light-sheet imaging of a non-obese diabetic mouse model of type I diabetes, we also characterized the infiltration of CD45 (also known as PTPRC)-labeled leukocytes in islets." (PMID 33158929, 2020).
rheumatoid arthritis (11 papers, 2015 to 2025). A chronic, systemic autoimmune disorder characterized by inflammation in the synovial membranes and articular surfaces. "For example, PTPRC is associated with response to antitumor necrosis factor-alpha therapy, which is a mainstay of treatment in rheumatoid arthritis." (PMID 35140805, 2022). "This work proved that the presence of LGALS9, PTPRC and CD44 in platelets could serve as a clinical indicator of rheumatoid arthritis." (PMID 35563556, 2022).
leukopenia (9 papers, 2013 to 2025). "Genetic engineering of the chimeric antigen receptor (CAR) binding epitope in CD45 (encoded by PTPRC) prevents engineered CAR-T cells from attacking each other (“fratricide”) and leukopenia by shielding benign hematopoietic blood cells through epitope editing of CD34+ cells." (PMID 40909481, 2025).
Hodgkins lymphoma (8 papers, 2007 to 2023). A heterogeneous group of malignant lymphoid neoplasms of B-cell origin characterized histologically by the presence of Hodgkin and Reed-Sternberg (HRS) cells in the vast majority of cases. "In human HEL cells, which were established from a patient with Hodgkin’s disease, the 100 different substrates identified included for example CD44, numerous integrins, ICAMs, IGF1R, NOTCH1/2, and PTPRC/CD45." (PMID 35371997, 2022).
metastatic carcinoma (8 papers, 2008 to 2024). A carcinoma which has spread from the original site of growth to another anatomic site. "Besides CD52 and PTPRC that were highly expressed by metastatic cancer cells of both TNBC and non-TNBC." (PMID 34611125, 2021).
metastatic prostate carcinoma (7 papers, 2015 to 2026). A carcinoma that arises from the prostate gland and has spread to other anatomic sites. "Our study establishes the existence and clinical relevance of CD45+CK18+ (PTPRC+KRT18+) hybrid CTC-like cells in metastatic prostate cancer." (PMID 41355965, 2026). "This study aimed to characterize circulating hybrid cells co-expressing KRT18 (pan-cytokeratin) and PTPRC (CD45), termed KP_Pos, in metastatic prostate cancer (mPCa), and to assess their molecular features, tumor microenvironmental (TME) origins, and clinical relevance." (PMID 41355965, 2026).
Miscarriage (7 papers, 2019 to 2025). A pregnancy that ends at a stage in which the fetus is incapable of surviving on its own, defined as the spontaneous loss of a fetus before the 22th week of pregnancy. "It has been reported that PTPRC is dysregulated in human miscarriage." (PMID 32792973, 2020). "Increased levels of PTPRC in the fetal membranes of sPTB indicated activation of T- and B-cell antigen receptor signaling and suggested that sPTB may share a common pathophysiological mechanism with miscarriage." (PMID 32792973, 2020).
multiple sclerosis (7 papers, 2006 to 2023). A progressive autoimmune disorder affecting the central nervous system resulting in demyelination. "A point mutation in PTPRC gene is strongly associated with multiple sclerosis in the German population." (PMID 28792504, 2017).
prostatitis (7 papers, 2016 to 2025). An infectious or non-infectious inflammatory process affecting the prostate gland. "In this study, CCR5, CD86, CD8A, ITGAM, and PTPRC were up-regulated and had the positive correlation with allograft rejection in kidney transplant patients." (PMID 36330810, 2022). "Five diagnostic genes were further identified, including CCR5, CD86, CD8A, ITGAM, and PTPRC, which were positively correlated with allograft rejection after the kidney transplant." (PMID 36330810, 2022). "High-throughput sequencing methods such as single-cell RNA-seq have enabled deep characterization of the prostate BCC genome, revealing key driver mutations of CASC5, NUTM1, PTPRC, KMT2C, and TBX3, genes also involved in chromatin remodeling and stem cell regulation." (PMID 40124187, 2025). "Thus, it can be seen that PTPRC, CD86, CCR5, and ITGAM could be considered as potential targets of PREDNISONE, EPOETIN BETA, ABATACEPT, MARAVIROC, and CLARITHROMYCIN, which may provide novel treatment options for kidney transplant patients with allograft rejection." (PMID 36330810, 2022).
severe combined immunodeficiency (7 papers, 2015 to 2025). Severe combined immunodeficiency (SCID) comprises a group of rare monogenic primary immunodeficiency disorders characterized by a lack of functional peripheral T lymphocytes resulting in early-onset severe respiratory infections and failure to thrive. "Inactivating mutations in PTPRC, for example, are responsible for some autosomal recessive cases of severe combined immunodeficiency (SCID), and SNP rs17612,648 confers a susceptibility risk for viral infections." (PMID 36755664, 2022). "Mutations in PTPRC have been identified in patients with autosomal recessive severe combined immunodeficiency (SCID); while, pathogenic mutations in NR5A2 have not been reported for any Mendelian disease." (PMID 32248360, 2020).
small cell lung carcinoma (7 papers, 2018 to 2025). Small cell lung cancer (SCLC) is a highly aggressive malignant neoplasm, accounting for 10-15% of lung cancer cases, characterized byrapid growth, and early metastasis. "Missense mutations were the most common in pan-cancer SNV analysis of target genes, and PTPRC had the highest proportion of SNVs in pan-cancer samples, which was particularly prominent in small cell lung cancer." (PMID 38165493, 2024).
epilepsy (6 papers, 2021 to 2025). A brain disorder characterized by episodes of abnormally increased neuronal discharge resulting in transient episodes of sensory or motor neurological dysfunction, or psychic dysfunction. "Using the example of epilepsy-associated gene PTPRC, we found a reduction in the DNA methylation (hypomethylation) level and an increase in transcription in the PZ compared with NIZ." (PMID 39541170, 2025).
mastitis (6 papers, 2018 to 2024). Inflammation of breast tissue during lactation or postpartum due to an obstructed duct or infection. "There was much higher expression of PTPRC in the mastitis sample compared to the adjacent breast in both participants." (PMID 30181507, 2018). "In addition, if the last feature exceeded 14.390 and the expression of IDH1 was present, PTPRC would be classified as having mastitis." (PMID 34691146, 2021). "The significance of the LOC407171, PTPRC, ABCG2, and IDH1 genes in the turquoise module was confirmed using DT models and attribute weighting, highlighting their critical roles in mastitis." (PMID 34691146, 2021). "PTPRC is a highly connected gene in PPI networks and is involved in the development of mastitis." (PMID 34691146, 2021).
teratoma (6 papers, 2015 to 2025). A non-seminomatous germ cell tumor characterized by the presence of various tissues which correspond to the different germinal layers (endoderm, mesoderm, and ectoderm).
head and neck cancer (5 papers, 2016 to 2025). A primary or metastatic malignant neoplasm affecting the head and neck. "The expression level of PTPRC has been reported to increase in head and neck cancer and has a protective effect for survival in ER-negative breast cancer." (PMID 34612148, 2021).
medulloblastoma (5 papers, 2009 to 2026). A malignant, invasive embryonal neoplasm arising from the cerebellum. "DIPG, ATRT, and SHH-activated medulloblastoma tumors had an increase in leukocytes compared to normal brain based on PTPRC (CD45) expression." (PMID 41541220, 2026).
T-cell acute lymphoblastic leukemia (5 papers, 2017 to 2024). Acute lymphoblastic leukemia of T-cell origin. "Protein tyrosine phosphatase receptor type C (PTPRC) codes for the protein tyrosine phosphatase CD45 (tumor suppressor) which has been shown to be present in T-cell acute lymphoblastic leukemia." (PMID 28450890, 2017). "Consistently, previous works identified PTPRC (CD45) as a potential prognostic marker since PTPRC higher expression correlated with a poor prognosis in precursor B-cell and T-cell acute lymphoblastic leukemia." (PMID 36698412, 2022).
allergic reaction (4 papers, 2019 to 2022). "PKC and ceramide can also activate the STAT3 pathway and then act on NF-κB and PTPRC, thus regulating allergic reaction." (PMID 35804699, 2022).
periodontal disease (4 papers, 2020 to 2025). "In the context of PT-driven inflammation, local immune activation resulting from periodontal disease may facilitate the migration, activation, and proliferation of immune cells via PTPRC, thereby exacerbating the inflammatory milieu characteristic of RA." (PMID 39987090, 2025).
skin cutaneous melanoma (4 papers, 2021 to 2023). "The risk model combining the PTPRC and TNM classifications holds the potential to be a promising tool for prognostic prediction of cutaneous melanoma." (PMID 37996489, 2023).
atopic dermatitis (3 papers, 2021 to 2023). "We present a 6-year-old male patient with markedly elevated IgE and severe atopic dermatitis presenting with staphylococcal bacteremia found to have a heterozygous variant in FLG (p.S3247X) and multiple variants of unknown significance in BCL11B, ZAP70, LYST, and PTPRC." (PMID 34603803, 2021).
cervical tumors (3 papers, 2015 to 2023). "High percentage of protein tyrosine phosphatase receptor-type C+ (PTPRC+) cells in cervical tumor are associated with enhanced tumor-infiltration by T-BET+ cells and FOXP3+ cells." (PMID 36905477, 2023). "A higher percentage of cervical tumors occupied by PTPRC+ cells were strongly associated with enhanced tumor-infiltration by Tbet+ cells and Foxp3+ cells." (PMID 33946372, 2021).
Listeria infection (3 papers, 2011 to 2022). "Therefore, these compounds could be considered for use as a potential treatment for listeriosis by inhibiting proteins such as, IL2, MAPK1, SRC, EGFR, PTPRC, TNF, IL1B, and ERBB2." (PMID 36671206, 2022).
liver cirrhosis (3 papers, 2022 to 2023). "Genes related to senescence (e.g., PTPRC, TIGIT, and TNF) and exhaustion (e.g., PDCD1, CTLA4, LAG3, and TNFRSF9) were highly enriched in CD4+ and CD8 + T cells from the participants with liver cirrhosis." (PMID 37735474, 2023). "We found significantly higher expression of markers of T-cell senescence (e.g., PTPRC, TIGIT, and TNF) and exhaustion (e.g., PDCD1, CTLA4, LAG3, and TNFRSF9) in hepatic CD4+ and CD8 + T cells in participants with NASH or liver cirrhosis than in controls." (PMID 37735474, 2023).
papillary thyroid carcinoma (3 papers, 2021 to 2025). "PTPRC, also known as CD45 antigen, has an important role in T and B cell activation and is associated with a poor prognosis of papillary thyroid carcinoma." (PMID 34795689, 2021).
seminoma (3 papers, 2006 to 2025). A radiosensitive malignant germ cell tumor found in the testis (especially undescended), and extragonadal sites (anterior mediastinum and pineal gland). "To further examine the functions of MMP9 and CTSK in seminoma, we subset immune cells (PTPRC+), and explored the expression patterns of markers for T cells (CD3D+ and CD3E+) and B cells (CD79B+; MS4A1+ and SDC1+)." (PMID 38123589, 2023).
synovitis (3 papers, 2020 to 2023). Inflammation of a synovial membrane. "Except for LCP1, CTSZ and PTPRC, all proteins have never been described in human synovitis." (PMID 35008858, 2021).
chronic myeloid leukemia (2 papers, 2018 to 2022). "Remarkably, phosphatases can influence the response to TKI treatment as reported for PTPN1 (PTP1B), PTPN6 (SHP1) and PTPRC (CD45) for BCR-ABL TKIs treatment in chronic myeloid leukemia or for PTPN11 (SHP2) for acquired resistance to ALK-TKIs in ALK-rearranged non-small cell lung cancer (NSCLC)." (PMID 36698412, 2022).
germ cell tumor (2 papers, 2013 to 2021). A benign or malignant, gonadal or extragonadal neoplasm that originates from germ cells. "The expression of PTPRC is highly associated with the methylation in testicular germ cell tumors (TGCT)." (PMID 34633989, 2021).
herpes simplex encephalitis (2 papers, 2014 to 2016). Herpes simplex virus encephalitis (HSE) is caused by the infection of the central nervous system by Herpes simplex virus (HSV) that could have a devastating clinical course and a potentially fatal outcome particularly with delay or lack of treatment. "PTPRC (protein tyrosine phosphatase receptor C) has recently been associated with herpes simplex encephalitis susceptibility in mice." (PMID 25290448, 2014).
leprosy (2 papers, 2023 to 2024). Leprosy is a chronic infectious disease affecting primarily the skin and peripheral nervous system. "LCK can determine the T cell signaling via regulating the phosphorylation of various signaling molecules and interact with negative regulators CD45(PTPRC) leadding to T cell hyporesponsiveness in leprosy progression." (PMID 38739634, 2024).
lupus nephritis (2 papers, 2017 to 2024). Glomerulonephritis in the context of systemic lupus erythematosus. "In the comparison of 62 subgroups, the up-regulated gene (PTPRC, MX1) and the down-regulated DEGs (EGR1, MME, RORC, ZBTB16, FKBP5) were verified to have mostly consistent change trends in all Lupus Nephritis vs. Normal Kidneys group with the results of GSE200306." (PMID 39301055, 2024).
neuroendocrine tumors (2 papers, 2021 to 2022). "The lowest MHC I and PTPRC gene expression were found in neuroendocrine tumors, including not only SCLC but also carcinoids, suggesting these NE tumors with decreased MHC I have fewer immune infiltrates." (PMID 33750914, 2021).
pericarditis (2 papers, 2022 to 2024). An inflammatory process affecting the pericardium. "There have been some studies on CCL2, CD8A, and PTPRC in cardiovascular diseases; however, their roles in pericarditis require further research." (PMID 38455049, 2024).